LIME1 (Lck interacting transmembrane adaptor 1)
Description:
Involved in BCR (B-cell antigen receptor)-mediated signaling in B-cells and TCR (T-cell antigen receptor)-mediated T-cell signaling in T-cells. In absence of TCR signaling, may be involved in CD4-mediated inhibition of T-cell activation. Couples activation of these receptors and their associated kinases with distal intracellular events such as calcium mobilization or MAPK activation through the recruitment of PLCG2, GRB2, GRAP2, and other signaling molecules.
Synonyms: LIME; FLJ20406; dJ583P15.4
Tractability: Antibody: UniProt places it where antibodies can reach, with high confidence; UniProt predicts a signal peptide or a membrane-spanning region; its Gene Ontology location is reachable by antibodies, with medium confidence. PROTAC: ubiquitination databases record sites on it.
Gene: Protein-coding gene on chromosome 20 (63,736,283 to 63,739,106, forward strand). Ensembl gene ENSG00000203896.
Subcellular location: Cell membrane
Gene Ontology:
Molecular function: protein binding; protein kinase binding
Biological process: B cell receptor signaling pathway; T cell receptor signaling pathway
Cellular component: extracellular region; B cell receptor complex; plasma membrane
Genetic constraint (gnomAD): Loss-of-function variants: 23 observed, 13.13 expected, observed/expected ratio (o/e) 1.75, 90% interval 1.21 to 1.96. The upper end of that interval is the gene's LOEUF score, 1.96, which puts it in group 6 of 6, group 1 being the genes least tolerant of losing a copy. Missense variants: 423 observed, 323.01 expected, observed/expected ratio (o/e) 1.31, 90% interval 1.21 to 1.42. Synonymous variants: 177 observed, 146.71 expected, observed/expected ratio (o/e) 1.21, 90% interval 1.07 to 1.37.
Homologues: Orthologues: chimpanzee LIME1 (98% identical), macaque LIME1 (92% identical), mouse Lime1 (56% identical), rat Lime1 (55% identical), pig LIME1 (52% identical), dog LIME1 (49% identical), Drosophila melanogaster CG4709 (13% identical), Caenorhabditis elegans zgpa-1 (9% identical). Paralogues in human: ZGPAT (13% identical), TFIP11 (13% identical).
Diseases named in the same sentence as LIME1 in open-access papers:
LIME1 is named in the same sentence as 8 diseases in open-access papers, as found by Europe PMC text mining. Sharing a sentence is not in itself a finding about the gene and the disease. The quoted sentences say what the papers report.
allergic disease (2 papers, 2024 to 2025). An immune response that occurs following re-exposure to an innocuous antigen, and that requires the presence of existing antibodies against that antigen. "Notable genes associated with allergy, immune responses, and inflammation were found (LCK, BACH2, SATB1, LIME1, KSR1, BCL11B, TCF1, and EVL)." (PMID 41394805, 2025). "A total of 55 CpG sites were found to significantly impact the risk of 5 site-specific allergic diseases, with 4 CpG sites exhibiting cross-allergic effects: cg17272563 (PRRT1), cg03689048 (BAT3), cg20069688 (STK19), and cg20513976 (LIME1)." (PMID 39640897, 2024).
asthma (1 paper, 2023). "The elevated genes include those associated with cellular proliferation (BRICD5), those previously associated with asthma and other inflammatory diseases (IL1RL1, IL6R) and those involved in inflammatory cell signaling (LIME1) and function (SLC11A1)." (PMID 37876037, 2023). "Additionally, uPAR overexpression universally caused changes in the expression of genes related to cellular proliferation (BRICD5) and T‐cell/B‐cell signaling (LCK/LIME1) and importantly asthma via the IL33 receptor (IL1RL1), now a target for new asthma drugs." (PMID 37876037, 2023).
cerebral palsy (1 paper, 2021). A group of disorders affecting the development of movement and posture, often accompanied by disturbances of sensation, perception, cognition, and behavior. "The transcription start site of the LIME1 gene, which has a key role in inflammatory pathways such as MAPK signaling, has been implicated in the pathophysiology of cerebral palsy." (PMID 33572947, 2021).
ovarian carcinoma (1 paper, 2021). A malignant neoplasm originating from the surface ovarian epithelium. "Among 86 genes linked to ovarian cancer in previous publications, our data contained expression values for 42, and of these, tests of LIME1, GPR162, STAB1, and SKAP1, resulted in unadjusted p<0.05." (PMID 34449791, 2021). "Among genes previously linked to ovarian cancer, tests of LIME1, GPR162, STAB1, and SKAP1 resulted in unadjusted p-values <0.05." (PMID 34449791, 2021).
tumor (3 papers, 2021). "We identified eight overexpressed and mutated tumor antigens with poor prognostic value of PRAD, including KLHL17, CPT1B, IQGAP3, LIME1, YJEFN3, KIAA1529, MSH5 and CELSR3." (PMID 34872584, 2021). "The amplification of genes such as COL5A1, IDO1, and GOLIM4 were in accordance with their higher expression in tumor samples, whereas no significant change of protein or phosphorylation levels was observed for genes with genomic amplification, such as CD4, CD7, LIME1, UNC93B1, C1S, C1R, or C8G." (PMID 34400640, 2021).
cancer (1 paper, 2022). A tumor composed of atypical neoplastic, often pleomorphic cells that invade other tissues. "The eight cross-cancer CpGs were annotated to genes involved in transport (KCNA3, KCNAB3 and TRAPPC1), signal transduction (AGAP3 and LIME1), microtubule assembly (FES and SHROOM1), and metal binding (FURIN and AGAP3)." (PMID 35710732, 2022).
LIME1 also shares sentences with these, for which no sentence is quoted: Allergy (1 paper); gastric cancer (1).